HMOX1 (heme oxygenase 1)
Description:
[Heme oxygenase 1]: Catalyzes the oxidative cleavage of heme at the alpha-methene bridge carbon, released as carbon monoxide (CO), to generate biliverdin IXalpha, while releasing the central heme iron chelate as ferrous iron. Affords protection against programmed cell death and this cytoprotective effect relies on its ability to catabolize free heme and prevent it from sensitizing cells to undergo apoptosis. [Heme oxygenase 1]: (Microbial infection) During SARS-COV-2 infection, promotes SARS-CoV-2 ORF3A-mediated autophagy but is unlikely to be required for ORF3A-mediated induction of reticulophagy. [Heme oxygenase 1 soluble form]: Catalyzes the oxidative cleavage of heme at the alpha-methene bridge carbon, released as carbon monoxide (CO), to generate biliverdin IXalpha, while releasing the central heme iron chelate as ferrous iron.
Synonyms: HO-1; bK286B10; HMOX1D; HSP32
Tractability: Small molecule: a structure with a bound ligand is known; a high-quality ligand is known; it has a high-quality binding pocket. Antibody: UniProt predicts a signal peptide or a membrane-spanning region. PROTAC: ubiquitination databases record sites on it; its protein half-life has been measured; a small molecule that binds it is known.
Target class: Enzyme; Oxidoreductase
Gene: Protein-coding gene on chromosome 22 (35,380,361 to 35,394,214, forward strand). Ensembl gene ENSG00000100292.
Subcellular location: Endoplasmic reticulum membrane
Subcellular location (Human Protein Atlas): Golgi apparatus; Plasma membrane
Pathways (Reactome):
Cellular responses to stimuli: Cytoprotection by HMOX1; Heme signaling; NFE2L2 regulating anti-oxidant/detoxification enzymes; Regulation of HMOX1 expression and activity
Immune System: Interleukin-4 and Interleukin-13 signaling; The NLRP3 inflammasome
Disease: Purinergic signaling in leishmaniasis infection
Metabolism: Heme degradation
Protein localization: Insertion of tail-anchored proteins into the endoplasmic reticulum membrane
Transport of small molecules: Iron uptake and transport
Gene Ontology:
Molecular function: heme binding; heme oxygenase (decyclizing) activity; identical protein binding; protein binding; protein homodimerization activity; structural molecule activity; enzyme binding
Biological process: cellular response to heat; erythrocyte homeostasis; heme catabolic process; heme oxidation; intracellular iron ion homeostasis; multicellular organismal-level iron ion homeostasis; negative regulation of extrinsic apoptotic signaling pathway via death domain receptors; negative regulation of ferroptosis; negative regulation of smooth muscle cell proliferation; positive regulation of angiogenesis; positive regulation of blood vessel endothelial cell proliferation involved in sprouting angiogenesis; positive regulation of canonical NF-kappaB signal transduction; positive regulation of cell migration involved in sprouting angiogenesis; positive regulation of smooth muscle cell proliferation; response to nicotine; response to oxidative stress; wound healing involved in inflammatory response; angiogenesis; endothelial cell proliferation; intracellular signal transduction; low-density lipoprotein particle clearance; negative regulation of cytokine production involved in inflammatory response; negative regulation of inflammatory response; negative regulation of leukocyte migration; positive regulation of chemokine production; and 4 more
Cellular component: endoplasmic reticulum; endoplasmic reticulum membrane; perinuclear region of cytoplasm; cytosol; extracellular region; membrane; mitochondrial outer membrane; nucleoplasm; nucleus; plasma membrane
Genetic constraint (gnomAD): Loss-of-function variants: 22 observed, 26.08 expected, observed/expected ratio (o/e) 0.84, 90% interval 0.6 to 1.2. The upper end of that interval is the gene's LOEUF score, 1.2, which puts it in group 5 of 6, group 1 being the genes least tolerant of losing a copy. Missense variants: 377 observed, 388.38 expected, observed/expected ratio (o/e) 0.97, 90% interval 0.89 to 1.06. Synonymous variants: 153 observed, 158.72 expected, observed/expected ratio (o/e) 0.96, 90% interval 0.84 to 1.1.
Gene-disease validity (ClinGen):
ClinGen rates the evidence that HMOX1 causes each of these diseases.
heme oxygenase 1 deficiency (autosomal recessive): Strong.
Homologues: Orthologues: chimpanzee HMOX1 (100% identical), macaque HMOX1 (96% identical), dog HMOX1 (87% identical), rabbit HMOX1 (84% identical), pig HMOX1 (82% identical), mouse Hmox1 (82% identical), rat Hmox1 (79% identical), guinea pig HMOX1 (74% identical), tropical clawed frog hmox1 (59% identical), zebrafish hmox1a (45% identical), Drosophila melanogaster Ho (23% identical). Paralogues in human: HMOX2 (45% identical).
Diseases named in the same sentence as HMOX1 in open-access papers:
HMOX1 is named in the same sentence as 770 diseases in open-access papers, as found by Europe PMC text mining. Sharing a sentence is not in itself a finding about the gene and the disease. The quoted sentences say what the papers report.
diabetes (309 papers, 2007 to 2026). "In the previous studies, only limited data were available regarding the role of HMOX1 gene polymorphism in people with diabetes." (PMID 40826355, 2025). "A GT(n) repeat length in the heme oxygenase 1 gene (HMOX1) has been widely associated with a variety of phenotypes, including susceptibility to and outcomes in diabetes, cancer, infections, and neonatal jaundice." (PMID 37414746, 2024). "Because pneumonia, COPD, and diabetes have all previously been identified as having an association with the HMOX1 promoter repeat, we extracted data on these clinical variables from the PheWAS analysis." (PMID 37414746, 2024). "Losartan, as an angiotensin II Type 1 receptor antagonist, can reduce the apoptosis of spinal cord neurons caused by diabetes through the activation of the nuclear factor erythroid 2-related factor 2/heme oxygenase 1 system (Nrf2/HO-1)." (PMID 39125694, 2024). "Enhancement of this gene has shown to alter diabetes development and polymorphisms in the Hmox1 gene promotor are thought to increase the risk for the development of T2D." (PMID 35580081, 2022). "We show that mice with a heterozygous deletion of Hmox1 alleles are prone to accelerated diabetes-induced structural and ultrastructural damage of the glomerular capillary with accentuated microalbuminuria." (PMID 29359167, 2017). "Diabetes is associated with reduced expression of heme oxygenase-1 (HO-1), a heme-degrading enzyme with cytoprotective and proangiogenic properties." (PMID 25889676, 2015). "For example, transferrin receptor (TFRC), hemochromatosis (HFE), and heme oxygenase 1 (HMOX1) are associated with an increased risk of diabetes, while transmembrane protease, serine (TMPRS), and mothers against decapentaplegic homolog 7 (SMAD7) are associated with a decreased risk." (PMID 40871742, 2025). "Notably, only a few studies have addressed the role of HO-1 or the HMOX1 gene polymorphism in cardiovascular complications in diabetes, and these studies have focused on T2D or gestational diabetes but not T1D." (PMID 40826355, 2025). "If not an artifact of sample size, this might again point to the notion that bilirubin has less to do with causing diabetes but rather is a consequence of diabetes (e.g. released upon activation of heme oxygenase-1 in response to oxidative stress)." (PMID 38324554, 2024). "Recent research revealed that melatonin reduced kidney damage caused by diabetes and exerted neuroprotective effects by activating the Nrf2/heme oxygenase-1 (HO-1) pathway and increasing levels of the antioxidant enzymes HO-1 and NAD(P)H dehydrogenase [quinone] 1 (NQO1)." (PMID 33343809, 2020). "Furthermore, HMOX1 polymorphisms are associated with emphysema, coronary artery disease, and type 2 diabetes mellitus." (PMID 30024897, 2018). "Previous studies reported that the prevalence of diabetes was associated with HMOX1 polymorphisms." (PMID 30024897, 2018). "Heme oxygenase-1 (HO-1) has been implicated in cardiac dysfunction, oxidative stress, inflammation, apoptosis and autophagy associated with heart failure, and atherosclerosis, in addition to its recognized role in metabolic syndrome and diabetes." (PMID 24086665, 2013). "Furthermore, HMOX1 has been implicated in various pathological processes, such as doxorubicin-induced ferroptosis in cardiomyopathy and the regulation of ferroptosis in diabetes-induced endothelial injury." (PMID 41030501, 2025). "Particularly, the increase in Hmox1 gene expression might be associated with the cell protection against oxidative damage caused by progesterone, being considered a therapeutic target for diabetes and other oxidative stress diseases." (PMID 33014046, 2020). "Oral administration of EeSs boosted the expression of Sod1, Cat, Gpx-1, Hmox-1, and Nqo-1 mRNA levels in the diabetic mice liver, suggesting that EeSs has a strong antioxidant potential to quince free radicals and hence the ability to prevent diabetes-associated complication." (PMID 28607575, 2017).
diabetes (continued). "Evidence of hippocampal oxidative damage was most marked in mice with STZ-diabetes exposed to post-hypoglycaemic hyperglycaemia; these mice also showed induction of Nrf2 and the Nrf2 transcriptional targets Sod2 and Hmox-1." (PMID 37015997, 2023). "The aim of this study was to assess serum bilirubin concentrations and (TA)n and (GT)n microsatellite variations in the promoter regions of the UGT1A1 and HMOX1 genes, respectively, in patients with type 2 diabetes mellitus (T2DM)." (PMID 37445792, 2023). "It unveiled that HMOX1 plays a pivotal role in regulating diabetes-induced ferroptosis in endothelial injury." (PMID 35498043, 2022). "In previous studies, Nrf-2 and its target HO-1 (heme oxygenase-1) showed protective effects against MI and reperfusion injury in patients with diabetes." (PMID 35795371, 2022). "The major complications of oxidative stress-induced diabetes are regulated by the nuclear factor erythroid 2-related factor 2 (Nrf2)/Heme oxygenase-1 (HO-1) pathway." (PMID 34804425, 2021). "For instance, increasing mRNA levels of heme oxygenase 1 (HO-1) and consequently protecting retinal cells from diabetes-induced oxidative stress." (PMID 33670455, 2021). "Taken together, these results suggest that puerarin protects podocytes from diabetes-induced injury through HMOX1 and Sirt1-mediated upregulation of autophagy, a novel mechanism explaining its renal protective effects in DN." (PMID 32116781, 2020). "In an experimental model of diabetes, the accumulation of FDP-lysine in Müller cells was increased and associated with an elevated level of heme oxygenase-1 (HO-1), a marker of oxidative stress." (PMID 33233661, 2020). "In the non-obese diabetic (NOD) mouse model, the proportion of CD206, heme oxygenase-1 (HO1) –positive “M2” macrophages (alternatively activated or anti-inflammatory) increased with development of diabetes." (PMID 30086735, 2018). "Lately, the upregulated heme oxygenase-1 (HO-1) in macrophages has been proposed as a crucially protective factor for ICC in diabetes." (PMID 29854081, 2018). "The goal of this study was to assess the role of HO-1 in the development of microvascular lesions within glomeruli during diabetes mellitus using a mouse model with specific alteration of the Hmox1 gene." (PMID 29359167, 2017). "In this respect, gastroparesis is similar to coronary artery disease, a complication of diabetes that has also been shown, in a study on a Chinese population with type 2 diabetes, to be more prevalent in people who have long GT repeats in their HMOX1 genes." (PMID 29161307, 2017). "Anthocyanins show protecting effects for inflammatory disorders and protect cells from diabetes-induced oxidant and inflammatory injuries by affecting Nrf-2/HO-1 (Nuclear factor erythroid 2-related factor 2/heme oxygenase-1) signal pathway." (PMID 28264426, 2017). "The effects of Hmox1 haploinsufficiency were studied as a means of assessing the intrinsic contribution of HO-1 in the development of renal microvascular lesions during diabetes." (PMID 29359167, 2017). "It is possible that bilirubin concentration increases in parallel with heme oxygenase-1 in the initiation phases of MetS and diabetes mellitus." (PMID 27936224, 2016). "Heme oxygenase-1, an important enzyme in the production of bilirubin, which is highly inducible, increases in early phases of diabetes and decreases in late stages." (PMID 27936224, 2016). "In this study, it was found that the rs6721961 (−617C/A) polymorphism of Nrf2 gene was associated with diabetes in Mexican mestizo men, while the rs7211 polymorphism of TXNIP gene and the rs2071749 polymorphism of HMOX1 gene were associated with obesity." (PMID 27274779, 2016). "Polymorphisms in HMOX1 and NQO1 have been associated with several oxidative stress-related diseases, including cancer, diabetes, and Alzheimer’s disease." (PMID 25933176, 2015).
diabetes (continued). "However, its ability to induce HMOX1 and form biologically active products has recently been implicated in beneficial effects in various experimental models including inflammatory bowel disease 38, diabetes 39, non-alcoholic liver disease 40, arterial hypertension 41 or sepsis." (PMID 25683492, 2015). "Brahma-related gene 1 (Brg1) is a key gene in inducing the expression of important endogenous antioxidant enzymes, including heme oxygenase-1 (HO-1) which is central to cardioprotection, while cardiac HO-1 expression is reduced in diabetes." (PMID 23853776, 2013). "Heme oxygenase-1 (HO-1) concentrations have been recently reported to be elevated in impaired glucose tolerance and type 2 diabetes mellitus (T2DM)." (PMID 23139759, 2012). "Moreover, overexpression of HMOX1 in diabetes and sickle cell disease exacerbates iron overload, resulting in ferroptosis of endothelial or cardiomyocytes." (PMID 41300309, 2025). "Metformin is a heme oxygenase-1 inhibitor, suggesting patients with diabetes using metformin may have lower bilirubin levels than patients not using metformin." (PMID 38324554, 2024). "In a study on rats with induced diabetes, astaxanthin proved to inhibit the activity of transcription factor NF-κB, to reduce oxidative stress and inflammatory mediators and to increase the levels of antioxidant enzymes like heme oxygenase-1 and peroxiredoxin." (PMID 38667772, 2024). "On the contrary, increases in bilirubin may be a reactive response to diabetes onset and occur due to increasing oxidative stress and subsequent stimulation of heme oxygenase-1, which then catalyzes formation of biliverdin and eventually, bilirubin." (PMID 38324554, 2024). "Although the importance and benefit of heme oxygenase-1 (HO-1) in diabetes rodent models has been known, the contribution of HO-1 in the pre-diabetic patients with hyperlipidemia risk still remains unclear." (PMID 38846488, 2024). "Moreover, thyme essential oil rich in monoterpenes is reported to upregulate the expression of Hmox1 and Nrf2, which are known to play an important role in cellular protection against oxidative stress in diabetes and cardiovascular diseases." (PMID 36079819, 2022). "Furthermore, previous studies have reported that heme oxygenase 1 (HO-1) abnormally expressed in retinal cells cultured in high glucose and in the retina of diabetes animal models." (PMID 32770964, 2020). "The role of HMOX1 and BLVRA in inflammation associated with diabetes has recently been reviewed." (PMID 32082188, 2020). "Furthermore, we focus on the translational potential of HIERS and heme oxygenase-1 (HO-1) in atherosclerosis, diabetes mellitus, and brain hemorrhage." (PMID 31357546, 2019). "In diabetes, increased oxidative stress at low heme oxygenase-1 levels and decreased insulin and insulin-like growth factor-1 signaling lead to loss of interstitial cells of Cajal, which results in abnormal gallbladder emptying and promotes gallstone formation." (PMID 31088424, 2019). "In view of liraglutide's antioxidative stress activity, we speculated that it could activate the nuclear factor erythroid 2-related factor (Nrf2)/heme oxygenase-1 (HO-1) pathway in the treatment of diabetes complicated with cerebral infarction." (PMID 29623090, 2018). "A particularly interesting property of M. Charantia polysaccharides, is their capacity to augment production of the cytoprotective heat shock protein heme oxygenase-1 (HO-1), at levels demonstrated to abate major symptoms of streptozotocin-induced diabetes and diabetic nephropathy in a rat model." (PMID 28335529, 2017). "This study investigates if treatment with an heme oxygenase 1 (HO-1) inducer, cobalt protoporphyrin IX (CoPP), could modulate the allodynia and hyperalgesia induced by diabetes and enhanced the antinociceptive effects of morphine." (PMID 26730587, 2016).